DNAJB5 (DnaJ heat shock protein family (Hsp40) member B5)
Synonyms: Hsc40
Tractability: PROTAC: ubiquitination databases record sites on it; its protein half-life has been measured.
Gene: Protein-coding gene on chromosome 9 (34,989,641 to 34,998,900, forward strand). Ensembl gene ENSG00000137094.
Subcellular location (Human Protein Atlas): Nucleoplasm; Cytosol
Gene Ontology:
Molecular function: protein binding; protein-folding chaperone binding
Biological process: response to unfolded protein; protein folding
Cellular component: cytosol; nucleus
Genetic constraint (gnomAD): Loss-of-function variants: 12 observed, 32.14 expected, observed/expected ratio (o/e) 0.37, 90% interval 0.24 to 0.61. The upper end of that interval is the gene's LOEUF score, 0.61, which puts it in group 2 of 6, group 1 being the genes least tolerant of losing a copy. Missense variants: 358 observed, 579.86 expected, observed/expected ratio (o/e) 0.62, 90% interval 0.56 to 0.67. Synonymous variants: 188 observed, 223.25 expected, observed/expected ratio (o/e) 0.84, 90% interval 0.75 to 0.95.
Homologues: Orthologues: macaque DNAJB5 (100% identical), rat Dnajb5 (99% identical), chimpanzee DNAJB5 (98% identical), dog DNAJB5 (97% identical), pig DNAJB5 (91% identical), guinea pig DNAJB5 (90% identical), mouse Dnajb5 (82% identical), rabbit DNAJB5 (75% identical), zebrafish dnajb5 (65% identical), tropical clawed frog dnajb5 (56% identical), Drosophila melanogaster CG5001 (45% identical), Drosophila melanogaster DnaJ-1 (42% identical), and 2 more. Paralogues in human: DNAJB4 (52% identical), DNAJB1 (52% identical), DNAJB13 (38% identical), DNAJB11 (27% identical), DNAJB6 (23% identical), DNAJB2 (21% identical), DNAJB7 (20% identical), DNAJB8 (19% identical), DNAJB12 (18% identical), DNAJB9 (17% identical), DNAJB14 (17% identical).
Diseases named in the same sentence as DNAJB5 in open-access papers:
DNAJB5 is named in the same sentence as 21 diseases in open-access papers, as found by Europe PMC text mining. Sharing a sentence is not in itself a finding about the gene and the disease. The quoted sentences say what the papers report.
breast carcinoma (1 paper, 2019). "All six thermogenes appear to be significantly overexpressed in breast cancer (HSPA1A, HSPA4), gliomas (DNAJB5), ovarian cancers (HSPA4, DNAJB5), pancreatic cancers (HSP90AA1), prostate cancer (HSP90AB1), thymic carcinoma (BAG1, HSP90AA1), and uterine cancers (HSPA4), as compared to normal tissue." (PMID 31814876, 2019).
cholangiocarcinoma (1 paper, 2023). A carcinoma that arises from the intrahepatic biliary tree (intrahepatic cholangiocarcinoma) or from the junction, or adjacent to the junction, of the right and left hepatic ducts (hilar cholangiocarcinoma). "Similarly, microRNA 21 (miRNA21) may mediate resistance to HSP90 inhibitors in cholangiocarcinoma (CCA) organoids by reducing DNAJB5 levels." (PMID 37693042, 2023).
stomach adenocarcinoma (1 paper, 2019). "In the stomach adenocarcinoma dataset, strong positive correlations in gene expression were identified between members of the small HSP family, including HSPB2, HSPB5 (CRYAB), HSPB6, HSPB7 and HSPB8, as well as the HSP40 family member DNAJB5, with superoxide dismutase (SOD3)." (PMID 30578123, 2019).
tumor (3 papers, 2018 to 2023). "MIR21 expression was confirmed to be inactivated in the tumor after withdrawal of doxycycline diet, while an increase in DNAJB5 protein expression was detected." (PMID 29113809, 2018). "The expression levels of DNAJB1, DNAJB5, DNAJB6, DNAJB11, DNAJB12, DNAJB13, and DNAJB14 were significantly upregulated in the tumor tissues." (PMID 32984053, 2020).
cancer (2 papers, 2019 to 2024). A tumor composed of atypical neoplastic, often pleomorphic cells that invade other tissues. "The six thermogenes include HSP90AA1 and HSPA4, common in thermoresistance and DAMPs/ICD, DNAJB5, the protein product of which has the highest estimated thermostability, and HSPA1A, HSP90AB1, and BAG1, which are implicated in cancer-relevant pathways (underlined)." (PMID 31814876, 2019).
myopathy (1 paper, 2024). A disease of the muscle in which the muscle fibers do not function properly. "Within this context, our analysis revealed correlations with several proteins, including BAG5, DNAJB4, and DNAJB5, which have plausible or confirmed roles in myopathy." (PMID 38392191, 2024).
neurological disease (1 paper, 2024). "We next sought to determine the levels and cellular localization of DNAJB5 in the human motor cortex of non-neurological disease controls and ALS and ALS + FTD cases." (PMID 38374041, 2024).
DNAJB5 also shares sentences with these, for which no sentence is quoted: brain tumor (1 paper); cardiac hypertrophy (1); glioma (1); infection (1); nervous system tumors (1); neurodegenerative disease (1); Obesity (1); osteosarcoma (1); ovarian carcinoma (1); pancreatic cancers (1); prostate carcinoma (1); sarcoma (1); thymic carcinoma (1); uterine cancer (1).